BCL2 (BCL2 apoptosis regulator)
Diseases named in the same sentence as BCL2 in open-access papers (continued):
Sharing a sentence is not in itself a finding about the gene and the disease.
cancer (continued). "By doing so, they promote SUFU turnover, impede its interaction with GLI and allow the expression of GLI target genes (including Bcl-2, Bcl-xL and Mcl-1) thus prompting the survival and growth of cancer cells." (PMID 29497611, 2018). "Increased resistance to apoptosis is a key oncogenic mechanism in several hematological malignancies and, in many cases, especially in lymphoid neoplasias, has been attributed to the upregulation of BCL-2." (PMID 29747654, 2018). "In this study, we further demonstrated that AUF1, as well as TTP, is involved in Bcl‐2 mRNA destabilization in cancer cells." (PMID 30524947, 2018). "We deduced that selective arresting of c-MYC promoter via stabilizing G-quadruplex activates a unique crosstalk with E2F-1 and VEGF-A, that concomitantly reduces BCL-2 expression triggering apoptosis in cancer cells." (PMID 30239898, 2018). "Many cancer cells are apt to be resistant to chemotherapeutic agents due to overexpression of prosurvival factors, such as Mcl-1, Bcl-2, and Bcl-xL." (PMID 29416631, 2018). "A common trend found among various types of cancers is a decrease in pro-apoptotic Bax and Bak and an increase in anti-apoptotic Bcl-2, Mcl-1, and Bfl-1 levels." (PMID 29904021, 2018). "Overexpression of Bcl-xl and Bcl-2 contributes to TRAIL resistance in various cancers, including HCC." (PMID 29444104, 2018). "Because anti-apoptotic BCL2 family proteins confer resistance of cancer cells to therapy, several selective inhibitors that target individual or multiple anti-apoptotic BCL2 proteins, have been developed." (PMID 29899841, 2018). "Here, addressing this need, we defined the landscape of BCL-2 gene dependencies in cancers derived from ten distinct tissues of origin." (PMID 30158527, 2018). "To find additional molecular targets to sensitize these resistant cell lines, we employed a negative-selection CRISPR screen using a library of sgRNAs that target a variety of cancer-related genes, including BCL-2 genes." (PMID 30158527, 2018). "The activated PI3K/Akt/mTOR pathway has been shown to decrease the BH3 (Bcl-2 homology domain) mimetic effectiveness in cancer cells by upregulating anti-apoptotic Bcl-2 family members, such as Mcl-1." (PMID 30110936, 2018). "In this way, BIRD-2 triggers Ca2+-mediated apoptotic cell death in cancer cells that depend for their survival on Bcl-2's anti-apoptotic function at the ER, such as the SU-DHL-4 DLBCL cells used in this study." (PMID 30416758, 2018). "This stabilization of BCL2 and BCLxL has been identified to control apoptosis and cell survival in multiple normal and cancer cells." (PMID 29361709, 2018). "This highlights an exciting strategy of utilizing Bcl-2 functional conversion to target chemoresistant cancers." (PMID 29899843, 2018). "Constitutive IP3 signaling has a pro-survival role in cancer cells, but it can be switched into pro-death signaling by disturbing Bcl-2/IP3R-complex formation with BIRD-2." (PMID 30416758, 2018). "Effect of compounds 13a and 15a on the active caspase-3 level, and the expression levels of Bcl-2 and Bax in HepG2 cancer cells treated with each compound at its IC50 concentration." (PMID 29944015, 2018). "In sum, we demonstrated that hyperosmotic stress enforced BCL-2 addiction of cancer cells and lowered the threshold for engagement of the mitochondrial cell death pathway." (PMID 29706657, 2018). "Lots of pathways are involved in the process of apoptosis, including Bcl-2/Bax and caspase system, and any disorder regulation of apoptosis often leads to cancer and tissue disorders." (PMID 29743971, 2018). "Bcl-2 protein is downregulated by the action of TA-1 on the HCT-116 cancer cells in a dose- and time-dependent manner." (PMID 30190788, 2018).
cancer (continued). "The anti‐apoptotic protein BCL2 is overexpressed in several cancers, and contributes to prolonged cell survival and chemoresistance, lending itself an excellent target for chemotherapeutics." (PMID 29460395, 2018). "Gossypol binds to the BH3 binding groove of anti-apoptotic Bcl-2 proteins, thus inhibiting the anti-apoptotic function of Bcl-2, Bcl-xl, and Mcl-1, and inducing apoptosis of cancer cells." (PMID 30459622, 2018). "Recent reports suggest that under conditions where apoptosis is inhibited, apoptosis inducing drugs, such as IAP and BCL-2 inhibitors, can induce necroptosis in cancer cells." (PMID 29615902, 2018). "BH3 mimetics are a class of anti-cancer drugs inhibiting the function of anti-apoptotic Bcl-2-protein family members like Bcl-2, Bcl-Xl, and Mcl-1145–147,148." (PMID 29491433, 2018). "Ca2+ release from ER as well as uptake by mitochondria are inhibited by several oncogenes like AKT, Bcl2, and K-Ras to trigger anti-apoptotic signalling in cancer cells." (PMID 28373964, 2017). "Some phytochemicals efficiently initiate the activation of caspase‐3 30 or raise the Bax/Bcl‐2 ratio 31 in cancer cells in vitro." (PMID 28524540, 2017). "It is known that members ofBcl-2 family genes have conserved domains called Bcl-2 homologydomains, which are differentially modulated in various cancers." (PMID 28099584, 2017). "These compounds have been developed as anti-cancer agents to counteract increased levels of Bcl-2 proteins often present in cancer cells." (PMID 28252652, 2017). "Application of a chemotherapeutic drug supported with a BH3 mimetic has the potential to overcome drug resistance in cancers overexpressing anti-apoptotic Bcl-2 proteins and thus increase the success rate of the treatment." (PMID 28252652, 2017). "It is conceivable that the upregulation of Bim or IP3R2 in cancer cells ought to be compensated by high anti-apoptotic Bcl-2 levels resulting in protein complexes with either Bim or IP3R2." (PMID 29340082, 2017). "Conversely, the elevated expression of some anti-apoptotic proteins, such as Bcl-xl and Bcl-2, prevents apoptosis of cancer cells." (PMID 28199969, 2017). "On the basis of PAK1-PUMA binding, we have revealed that single novel compound can suppress PAK1 activity and induce cell death only in PAK1 activated and Bcl-2 overexpressed cancer cells." (PMID 28423593, 2017). "A significant (P<0.01) increase of Bcl-2 in malignant tumors was observed, and in metastatic CMTs the evasion of apoptosis was also suggested." (PMID 28081183, 2017). "The cell-permeable Bcl-2/IP3R disruptor-2 (BIRD-2) peptide can kill these Bcl-2-dependent cancers by targeting Bcl-2’s BH4 domain, unleashing pro-apoptotic Ca2+-release events." (PMID 29340082, 2017). "VDAC1 is involved in the process of mitochondria-mediated apoptosis, mediating the release of apoptotic proteins and interacting with anti-apoptotic proteins, such as HK, Bcl-2 and Bcl-x, some of which are also highly expressed in many cancers, including GBM." (PMID 28412744, 2017). "The top three non-cancer disease genes regulated by the co-functional module and mapped to the pathways are MMP2, VEGFA and CASP8, while for the cancers are BCL2, MDM2 and VEGFA." (PMID 28340554, 2017). "For example, increased expression of anti-apoptotic Bcl-2 proteins that block the action of pro-apoptotic effectors (BAX and BAK) has been associated with cancer cell progression and resistance to pro-apoptotic signals." (PMID 29156771, 2017).
cancer (continued). "recently, it has been described the capacity of quercetin to directly bind the BH3 domain of Bcl-2 and Bcl-XL proteins, inhibiting their activity and promoting cancer cell apoptosis." (PMID 28489572, 2017). "In the current study, modulations in the expression of Bcl-2 had been correlated with the type of cancer cells." (PMID 28197098, 2017). "Given that increased levels of Bcl‐2 proteins have been reported in different cancer types correlating with chemotherapy resistance and poor prognosis [Miyashita & Reed, 1993], Bcl‐2 proteins have become a viable target for anticancer therapy." (PMID 28804913, 2017). "VDAC1 also regulates apoptosis via binding of apoptosis-regulating proteins, such as HK, Bcl-2 and Bcl-xL, some of which are also highly expressed in many cancers." (PMID 28412744, 2017). "Simultaneous application of a chemotherapeutic agent and a BH3 mimetic can potentially overcome drug resistance in cancers overexpressing anti-apoptotic Bcl-2 proteins and thus increase the treatment success rate." (PMID 28252652, 2017). "Some cancers with elevated Bcl-2 display poor responses towards BH3 mimetics, suggesting an additional function for anti-apoptotic Bcl-2 in these cancers." (PMID 29340082, 2017). "BH3 mimetics (e.g. ABT-199 (venetoclax)) kill cancer cells by targeting Bcl-2’s hydrophobic cleft and disrupting Bcl-2/Bim complexes." (PMID 29340082, 2017). "The levels of STAT3 have also been found to be elevated in many cancers where they stimulate cell proliferation (via cyclin D1) and induction of anti-apoptotic proteins (such as Bcl2)." (PMID 28467474, 2017). "Important regulators of these Ca2+ signals and the onset of cancer are the B-cell lymphoma 2 (Bcl-2) family of proteins." (PMID 28516063, 2017). "The variable expression of Bcl-2 in cancer cells demonstrates a gene structure and/or expression abnormalities dependent regulation." (PMID 28197098, 2017). "We also observed that exposure of CeO2-NCs to the HT29 cancer cell line altered the normal expression levels of Bcl2, BclxL, Bax, PARP, and cytochrome c proteins." (PMID 28634498, 2017). "Similar results were obtained with DNJ intake, which suggests that DNJ induces apoptosis in cancer cells through the Bcl-2/Bax signaling pathway." (PMID 28751809, 2017). "Often found to be upregulated in cancer and chemoresistance, anti-apoptotic Bcl-2 proteins such as Bcl-2, Bcl-XL and Mcl-1 inhibit Bax activation." (PMID 28424988, 2017). "Immunoblotting experiments confirmed the expression of Bcl-2 or Bcl-xL in stably transfected cancer cells." (PMID 28038464, 2017). "Although BCL-2 protein was investigated in various of cancers apoptosis studies, BCL-xL, a protein encoded by gene BCL2L1, is considered as a more effective marker than BCL-2." (PMID 28877725, 2017). "Another, small molecule ABT-737 that inhibits Bcl2, Bcl-xl or Bcl-w is a promising agent for treatment of cancers." (PMID 28137308, 2017). "BCL2, KRAS and VEGFA, most frequently mutated oncogenes in human cancer are overexpressed in different types of human malignancies." (PMID 28102286, 2017). "BCL-2 has been shown to interact with orphan nuclear receptor ‘Nur77’, which is required for cancer cell apoptosis and can be induced by many anti-neoplastic agents." (PMID 28509858, 2017). "Bcl-2-associated athanogene-1 exists as multiple protein isoforms that interact with diverse partners, including chaperones Hsc70/Hsp70, Ser/Thr kinase Raf-1 and Bcl-2, to promote cancer cell survival." (PMID 28510570, 2017). "Overexpression of anti-apoptotic proteins, such as Bcl-2 and Bcl-xL, has been demonstrated in numerous cancers, including colon, thyroid, breast, and endometrial cancer." (PMID 28824871, 2017). "ABT-263 inhibits selectively Bcl-2, Bcl-xl and Bcl-w in a wide range of human cancer cell lines (i.e., small cell lung cancer, ALL, NHL, myeloma)." (PMID 28464919, 2017). "Overall, these results demonstrate the decreasing the ratio of Bcl-2/Bax in 9f-treated MCF-7 cancer cells." (PMID 28814788, 2017).
cancer (continued). "By blocking polymerization of Bax, Bcl-2 suppresses apoptosis and contributes to drug resistance in cancer cells." (PMID 28537875, 2017). "Overall, our data indicate that BH4-domain-antagonizing tools like BIRD-2 hold potential to kill Bcl-2-dependent cancer cells, in particular those that are more resistant to chemotherapy and precision medicines like venetoclax." (PMID 29340082, 2017). "Bcl-2 is known to be a crucial anti-apoptotic protein and miRNA mediated Bcl-2 suppression has been demonstrated in a wide variety of cancers." (PMID 29041990, 2017). "Inhibition of Bcl-2 expression has been believed as an important treatment strategy for various cancers." (PMID 28884131, 2017). "In pathway in cancer, we found that Bcl2, VEGFA, PTEN, Jun, Fos, APC2 gene expression were up-regulated and the expression of Myc was down-regulated in the MMQ TSLCs." (PMID 28163656, 2017). "A high Δψm and a high Bcl2/Bax ratio are believed to promote cell proliferation and enhanced cell survival, thereby contributing to cancer progression." (PMID 28157696, 2017). "The reduction of Bcl-2/Bax protein and mRNA levels by matrine leads to an increase of cell cycle arrest in cancer cells." (PMID 28304343, 2017). "During the carcinogenesis of 26 kinds of cancers, averagely more than 70% of those cancers relate to the dysfunction of the three genes (BCL2, MDM2 and VEGFA)." (PMID 28340554, 2017). "We focused on Bax, a vital cell death regulator, is an indispensable gateway to mitochondrial dysfunction and a major proapoptotic member of the B-cell lymphoma 2 (Bcl-2) family proteins that control apoptosis in normal and cancer cells." (PMID 28697793, 2017). "Considering their expression in our cohort of patients, Bcl-2 was more expressed in malignant tumors than in healthy tissue and in benign tumors, as already reported in CMTs and in several human tumors." (PMID 28081183, 2017). "PD98059 inhibits phosphorylation of MEK, inactivates the oncogene bcl-2, and ultimately increases apoptosis of cancer cells." (PMID 29245959, 2017). "Diallyl trisulfide causes an increase in Bcl-2 inactivated in U87MG and SH-SY5Y cells; the active form of Bcl-2 is decreased in both cancer cell lines." (PMID 28852876, 2017). "EGCG and cisplatin alone, or in combination, reduced the levels of Bcl-xL and Bcl-2 in UMSCC 10B cancer cells." (PMID 28703809, 2017). "BCL-2 (B-Cell Lymphoma 2), a member of the human Bcl-2 family is one of the main anti-apoptotic genes and seems to be a good target for cancer therapy in the future." (PMID 28761826, 2017). "Evidence indicates that the inhibition of the PI3K/Akt/mTOR pathway primes cancer cells for mitochondrial apoptosis by tipping the balance toward antiapoptotic Bcl-2 proteins, resulting in increased mitochondrial outer membrane permeabilization." (PMID 28959140, 2017). "The anti-apoptotic factor Bcl-2 (B-cell lymphoma 2), an integral outer mitochondrial membrane protein, is also increased in cancer cells, while the pro-apoptotic protein BAX is downregulated." (PMID 30873475, 2017). "The anti-cancer effect was mainly mediated by cell cycle arresting, increasing ratio of Bax to Bcl-2 and cytochrome c releasing." (PMID 28184196, 2017). "We have further demonstrated how ligand-dependent conformational changes of BCL-2 i-motif or G-quadruplex topologies can modulate the BCL-2 expression in cancer cells." (PMID 29163897, 2017). "Overexpressed VDAC1 presents anchoring sites for the cancer overexpressed HK and for Bcl-2 and Bcl-xL, interactions that are important for their anti-apoptotic activities (see Modulation of VDAC1-Mediated Apoptosis and Metabolism VIA Interacting Proteins)." (PMID 28824871, 2017).
cancer (continued). "Plotting the IC50 values for the apoptotic effect of both Bcl-2 inhibitors revealed a reciprocal sensitivity between venetoclax and BIRD-2 in the cancer cells dependent on Bcl-2 for their survival." (PMID 29340082, 2017). "Overexpression of antiapoptotic Bcl-2 occurs in many cancer cells and prevents cell death induced by nearly all anticancer drugs and radiation." (PMID 28959140, 2017). "It has been well demonstrated that the over-expression of BCL2 proto-oncogene contributes to the resistance of cancer cells to apoptosis." (PMID 28386116, 2017). "Our findings suggest that some cancer cells require Bcl-2 proteins at the mitochondria, preventing Bax activation via its hydrophobic cleft, while others require Bcl-2 proteins at the ER, preventing cytotoxic Ca2+-signaling events via its BH4 domain." (PMID 29340082, 2017). "Related to this, ABT199/venetoclax-induced apoptosis in Bcl-2-dependent cancer cells appeared to occur independently of intracellular Ca2+ overload." (PMID 28516063, 2017). "First, we describe how ERK1/2 signalling controls the BCL2‐regulated, cell‐intrinsic apoptotic pathway and how this knowledge has recently been used to develop new drug combinations for the treatment of cancer." (PMID 28548464, 2017). "Altogether, our study highlights the need for mechanism-guided targeting of anti-apoptotic BCL-2 proteins to effectively activate the mitochondrial cell death programme to kill cancer cells." (PMID 28714472, 2017). "Overexpression of Bcl-2 stops apoptosis, whereas upregulation of Bax induces apoptosis in cancer cells." (PMID 29053567, 2017). "High Bcl-2 expression was detected in most cancer types, and it confers a poor prognosis due to its antiapoptosis effect." (PMID 28032603, 2017). "These include cancer hallmarks of various types: oncogenes (BCL2, BRAF), caspases (CASP6/7), transcription factors (E2F3), cell cycle genes (CDC42, CDK2, CDKN2A), cancer related kinases (JAK2/3, MAPK4/6/14) and DNA repair genes (BRCA1, PARP1 and RAD50)." (PMID 28059167, 2017). "The molecular mechanisms of action of tetrandrine in cancer cells include upregulation of Bax, Bak, Bad, and apaf-1, downregulation of Bcl-2 and Bcl-xl, releasing cytochrome c, and activation of caspase-3 and -9 in the apoptotic mitochondrial pathway." (PMID 28304343, 2017). "Over the years, it has become clear that Bcl-2 inhibition via targeting its BH4 domain has potential as an effective anti-cancer treatment." (PMID 28516063, 2017). "The Bcl-2 gene family members play important roles in the regulation of apoptosis and are frequently altered in cancers." (PMID 29156771, 2017). "Induction of apoptotic cell death by modulating the oncogenic signaling pathways, including JNK, Bax and Bcl-2, and PI3K/Akt and MAPK/ERK, has been suggested as the potential underlying mechanism of the anti-cancer effects of simvastatin." (PMID 28910332, 2017). "Unfortunately, some Bcl-2-dependent cancer cells are insensitive to BH3-mimetic compounds, likely due to low levels of Bim and/or of Bax/Bak." (PMID 29340082, 2017). "The down-regulation of Bcl-2/Bax ratio has been also founded being accompanied by the activation of caspase family in the experiments on PAB-treated cancer cells." (PMID 28701952, 2017). "More specifically, BAX exerts pro-apoptotic activity while BCL-2 is an anti-apoptotic protein that inhibits apoptosis and is overexpressed in cancer." (PMID 29340085, 2017). "Given that the interplay between Bax and Bcl-2 is capable of controlling anti-cancer drug-induced apoptosis, we examined the expression of Bax and Bcl-2." (PMID 28178656, 2017). "The methanolic leaf extract of Datura innoxia has shown to induce apoptosis in human colon adenocarcinoma (HCT 15) and larynx (Hep-2) cancer cell lines via inhibiting the expression of antiapoptotic Bcl-2 protein." (PMID 28728544, 2017). "miR34 is involved in cancer stem cell self-renewal via regulation of downstream targets Notch1/2 and Bcl-2." (PMID 28881855, 2017).